AR (androgen receptor)
Diseases named in the same sentence as AR in open-access papers (continued):
Sharing a sentence is not in itself a finding about the gene and the disease.
prostate carcinoma (continued). "Therefore, therapeutic approaches that can diminish the availability of both AR-FL and AR-Vs should offer considerable benefit in preventing and inhibiting prostate cancer recurrence after androgen deprivation therapy." (PMID 25375370, 2014). "For example, the prostate cancer associated AR mutations H874Y and T877A can be activated by non-androgenic hormones (e.g. oestradiol and progesterone) and antiandrogens (e.g. CPA and OHF)." (PMID 24659630, 2014). "Elucidating this process may be critical for development of AMPK activators as therapeutics to treat advanced prostate cancer, given the multitude of mechanisms by which AR is reactivated after hormone therapy." (PMID 24562461, 2014). "This reliance on AR signaling makes androgen depravation therapy (ADT) an effective way to limit prostate cancer tumor growth; initially tumors respond well to anti-androgen therapy, dramatically shrinking in size and patients see a reduction in cancer symptoms." (PMID 24722453, 2014). "Because it is driven primarily by androgen receptor (AR) signaling, advanced prostate cancer is typically treated by androgen deprivation therapy, in which surgical or medical castration is performed to block active AR signaling either by eliminating the ligand or affecting the receptor directly." (PMID 24971999, 2014). "Interestingly, while AR has been shown to directly inhibit PTEN transcription in prostate cancer cells, AR has been reported to activate PTEN transcription in breast cancer cells." (PMID 25103565, 2014). "We hypothesized that androgen receptor (AR) signaling, which plays an essential role in the disease, mediated prostate cancer cell growth in part by increasing flux through the pentose phosphate pathway." (PMID 24861463, 2014). "It has been shown that AKT phosphorylation and activity stimulated ligand-independent AR activation could contribute to castration resistant growth of prostate cancer cells." (PMID 25296973, 2014). "To understand the mechanism(s) behind G6PD activation, we hypothesized that AR signaling, elevated in the majority of prostate cancers, regulated the levels of this key enzyme." (PMID 24861463, 2014). "In this study, we identified AR as a degradation substrate of SPOP in prostate cancer cells." (PMID 24508459, 2014). "Importantly in terms of prostate cancer treatment LNCaP-abl cells, which represent a model of castration resistant prostate cancer with gain of AR function, were also highly sensitive to metformin treatment." (PMID 24484909, 2014). "Since IL-6 was shown to activate AR signaling, increased levels of IL-6 during androgen deprivation may enhance the survival and proliferation of prostate cancer cells." (PMID 24296978, 2014). "In summary, these experiment support our hypothesis that activation of cAMP signaling mediates NED promotion by high cell density in AR-positive prostate cancer cell lines." (PMID 24884804, 2014). "Given the importance of AR in prostate cancer initiation, progression, and therapy resistance, identification of AR as a substrate of SPOP E3 ligase provides a plausible explanation for the high frequency of SPOP mutations in prostate cancer." (PMID 24508459, 2014). "Effects of RSV and FIDAS on AR- and AR-V7-mRNA-expression in prostate cancer cell lines." (PMID 24887556, 2014). "Also this study revealed that reverse correlation of RAR beta 2, ER alpha, PGR, and RGMA expressions with EZH2, SRC3, and AR expressions in prostate cancer tissues suggests that these genes are the target of EZH2." (PMID 25535400, 2014). "Therefore, it is understandable that miRNA mediated control of AR is lost in TMPRSS2-ERG positive prostate cancer and ELAVL1 stabilizes the expression of AR and ERBB2 which synchronously trigger the expression of cancer promoting genes." (PMID 24739220, 2014). "The growth and progression of prostate cancer depend largely on AR signaling." (PMID 24173286, 2014).
prostate carcinoma (continued). "Our previous studies revealed the occurrence of two important events in prostate cancer cells which were the loss of prostate specific membrane antigen (PSMA) expression and a cell signal pathway switch from AR to c-Met during long-term androgen deprivation in an established in vitro model." (PMID 24297527, 2014). "Importantly, we demonstrate that these factors are successful in inhibiting the AR in circumstances thought to lead to castrate resistant prostate cancer." (PMID 24659630, 2014). "Very recently, we could also show that the anti-tumor effect of metformin in prostate cancer cells is in part caused by its disruptive effect on the MID1 protein complex and the subsequent downregulation of the AR protein." (PMID 24913494, 2014). "For example, the human prostate cancer VCaP cells are TMPRSS2-ERG positive with wild type AR, whereas human prostate cancer LNCaP cells are TMPRSS2-ERG negative with mutated AR." (PMID 24739220, 2014). "Therefore, it is necessary for novel strategies to effectively eliminate AR signaling from prostate cancer for the clinical control of this lethal disease." (PMID 24573652, 2014). "AR is also important for initiation and progression of prostate cancer." (PMID 24508459, 2014). "One report revealed the important roles of endothelial cells within the prostate cancer microenvironment to promote the prostate cancer metastasis and provide new potential targets of IL-6-- > AR-- > TGFbeta-- > MMP-9 signals to battle the prostate cancer metastasis." (PMID 24397471, 2014). "In contrast, enzalutamide failed to enhance AR downregulation in C4-2 cells expressing the prostate-cancer-associated SPOP mutant F133V." (PMID 24508459, 2014). "Furthermore, studies demonstrate that androgens, via the androgen receptor, induce oxidative stress in normal and prostate cancer cells." (PMID 24614817, 2014). "In addition, other studies show anti-tumor effects of GSK-3β inhibition on prostate cancer cells in vitro, but these effects were predominantly attributed to modulating effects on the androgen-receptor axis, or changes in cell cycle proteins." (PMID 25344861, 2014). "The AR signalling pathway is a key factor in the development and progression of prostate cancer." (PMID 25535400, 2014). "The androgen receptor has long been a target for prostate cancer." (PMID 24598693, 2014). "AR plays a vital role in androgen-dependent prostate cancer growth." (PMID 24981574, 2014). "Imaging data of nanoscale microbubbles carrying AR siRNA in a C4-2 prostate cancer xenograft model." (PMID 24798477, 2014). "Also, it is well established that androgen receptor (AR) plays a critical role in prostate cancer cell proliferation, survival, and differentiation." (PMID 25535400, 2014). "Furthermore, it has been suggested that the androgen-activated AR acts also as a tumor suppressor for prostate cancer." (PMID 25216853, 2014). "For example, a study on prostate cancer found that the UBE2C oncogene interacts with two distal binding sites of Androgen Receptor (AR, an important protein in prostate cancer) only in Castration-Resistant Prostate Cancer (CRPC) cells but not in Androgen-Dependent Prostate Cancer (ADPC) cells." (PMID 24835279, 2014). "However in these prostate cancer cells when Art27 expression was repressed, Androgen Receptor target genes were up-regulated indicating a native Art27 repressive role." (PMID 24743694, 2014). "Notably, androgen and AR can transcriptionally and post-transcriptionally regulate the MiR-23a27a24-2 cluster in prostate cancer cells." (PMID 24739220, 2014). "Such a concept may lead to novel strategies for developing drugs that can alter AR conformation, thus facilitating E3 ligase-mediated destruction of AR in prostate cancer." (PMID 24508459, 2014).
prostate carcinoma (continued). "In their study, high levels of β-catenin is observed in human prostate cancer tissues, which is inversely linked with AR expression, raising the possibility that low or no AR expression activates Wnt/β-catenin signaling." (PMID 24618337, 2014). "The AR signaling pathway also plays critical roles in prostate cancer initiation and progression." (PMID 23755100, 2014). "Importantly, we used the LAPC-4 prostate cancer cell line as a control to define AR staining for these methods, since these cells express the wild-type AR." (PMID 25424879, 2014). "The AR drives both proliferation and anabolic pathways in prostate cancer cells." (PMID 25003216, 2014). "So the abnormal regulation of p68 may affect the function of AR influencing the development and progression of prostate cancer." (PMID 25150365, 2014). "AR has recently been implicated in the genesis of gene rearrangements in prostate cancer by facilitating double-strand DNA breaks and inducing non-homologous end-joining (reviewed in refs 17, 18)." (PMID 25255306, 2014). "Interestingly, ELK1 is obligatory for androgen receptor-dependent growth and survival of prostate cancer cells." (PMID 25504435, 2014). "Thus, blocking AR expression and activation in clinical practice has become one of the most effective approaches in prostate cancer therapy." (PMID 25296973, 2014). "Finally, our results suggest a role of cAMP signaling activation in NED promotion by high cell density in AR-positive prostate cancer cell lines." (PMID 24884804, 2014). "This study identifies AR as a bona fide substrate of SPOP and elucidates a role of SPOP mutations in prostate cancer, thus implying the importance of this pathway in resistance to antiandrogen therapy of prostate cancer." (PMID 24508459, 2014). "We report strong anti-AR activity of the natural product shikonin in prostate cancer cells." (PMID 24573652, 2014). "AR signaling is essentially required for most human prostate cancers." (PMID 25333263, 2014). "Prostate-cancer-associated mutants of SPOP cannot bind to and promote AR destruction." (PMID 24508459, 2014). "In our previous report, we demonstrated that AR directly regulates expression of INPP4B in prostate cancer cells, suggesting that castration may lead to a decline in INPP4B and activation of Akt signaling." (PMID 25248616, 2014). "Androgen receptor (AR) signalling plays a major role in prostate cancer development." (PMID 25216524, 2014). "LNCaP is an androgen-dependent human prostate cancer cell line and expresses predominantly AR-FL." (PMID 25375370, 2014). "EZH2 could impede epithelial differentiation and contribute to prostate cancer progression because it was shown to directly modulate the transcriptional output of AR." (PMID 25277175, 2014). "The proposed mechanism for these findings is as follows; in prostate cancer, androgen is bound to AR, which activates HIF-1α through a cascade of several protein kinase systems, continuously increasing expression of the HIF-1α-related gene, one of which is BNIP3." (PMID 25140630, 2014). "Furthermore, overexpression of NLK prompted a more effective induction of apoptosis in AR-expressing prostate cancer cells than in AR-negative cells." (PMID 24816797, 2014). "The same could be shown in another AR-positive prostate cancer cell line (LNCaP) and with other MID1-specific siRNAs." (PMID 24913494, 2014). "We hypothesized that G6PD could play a role in prostate cancer cell proliferation and further hypothesized that this could be regulated by AR, a central factor in prostate cancer." (PMID 24861463, 2014). "Inhibition of AKT phosphorylation and activity suppresses AR levels in prostate cancer." (PMID 25296973, 2014). "The AR has been shown to regulate prostate cancer metabolism by driving the expression of an extensive network of metabolic genes, such as fatty acid synthase and alpha-methylacyl-CoA racemase, resulting in stimulation of both aerobic glycolysis and anabolic pathways." (PMID 25003216, 2014).
prostate carcinoma (continued). "For instance, since COUP-TFII was reported to interact with androgen receptor (AR) to modulate its transcription activity in prostate cancer cells, COUP-TFII might be involved in the development of castration resistance prostate cancer (CRPC)." (PMID 25328664, 2014). "Abnormal AR expression in prostate cancer are correlated with metastasis and aggressiveness." (PMID 24397471, 2014). "The AR has generally been accepted as the pre-eminent driving protein in prostate cancer and, even in hormone resistant prostate cancer, it is still implicated in several escape mechanisms based on a non-dihydrotestosterone-bound-AR." (PMID 24737870, 2014). "As CDK11p58 was involved in the negative regulation of AR, we speculated that CDK11p58 might be involved in the regulation of prostate cancer metastasis." (PMID 24397471, 2014). "Although AR induction of INPP4B has been demonstrated for androgen-dependent human prostate cancer cell lines, it has remained unclear whether INPP4B would decline in clinically-derived human prostate cancer tissue during castration." (PMID 25248616, 2014). "The LNCaP cell line is an important model system to study AR-mediated signaling in prostate cancer." (PMID 25375165, 2014). "OCT1 is a coregulator of the androgen receptor (AR) and can be a prognostic factor for prostate cancer, which may lead to the development of a novel therapeutic intervention." (PMID 24932254, 2014). "The androgen receptor (AR) is a widely expressed ligand-activated transcription factor which mediates androgen signalling by binding to androgen response elements (AREs) in normal tissue and prostate cancer (PCa)." (PMID 24895212, 2014). "Combinatorial targeting of NEAT1 and AR may represent a unique therapeutic regimen within a subset of patients with advanced prostate cancer." (PMID 25415230, 2014). "Androgens interaction with the AR on prostate cancer cells stimulate proliferation and progression." (PMID 25053986, 2014). "AR is an important regulator of cellular growth in androgen-dependent prostate cancer cells." (PMID 24573652, 2014). "An recent study on animal model showed that thymoquinone suppresses the expression of AR and E2F-1 necessary for proliferation and viability of androgen-sensitive as well as androgen-independent prostate cancer cells both in vitro and in vivo and, interestingly, produced no clear side effects." (PMID 24959190, 2014). "Incubation of nuclear extract prepared from the AR expressing prostate cancer cell line LNCaP with either ARE or PSA-RE-III oligonucleotides produced several bands with virtually identical electrophoretic motilities, but not with the mutated AREm (lanes 1, 8 and 7, respectively)." (PMID 24895212, 2014). "This pioneer function is of particular importance in gene expression of endocrine-related cancers, including breast and prostate cancers as FoxA1 is a key cooperating factor for the nuclear hormone receptors, estrogen receptor-α (ER), and androgen receptor (AR)." (PMID 25401090, 2014). "Previous studies have reported the role of AR in regulating apoptosis in prostate cancer." (PMID 24658443, 2014). "The overexpression of AR promotes the migration and invasion of prostate cancer cells." (PMID 24397471, 2014). "Also AR mRNA expression shows significantly higher in prostate cancer when compared to benign prostatic tissue." (PMID 24397471, 2014). "Re-expression of CAMK2N1 in prostate cancer may provide clinical benefits to patients; however, further studies are warranted to determine the molecular mechanisms link between CAMK2N1 and androgen receptor signaling in prostate cancer." (PMID 25003983, 2014). "Furthermore, mesenchymal-to-epithelial transition (EMT) stimulated by TGF-β and its interplay with AR signaling is important for prostate cancer cell migration." (PMID 24484909, 2014). "And finally CDK11p58 could inhibit the metastasis of AR positive prostate cancer cells through inhibition of integrin β3 and MMP2." (PMID 24397471, 2014).
prostate carcinoma (continued). "In this study, we hypothesized that shikonin may have a role as an inhibitor of AR signaling and, thus, could serve as a therapeutic agent for the management of human prostate cancers." (PMID 24573652, 2014). "In addition to endocrine disorders, steroid receptors frequently assume malicious roles in cancer, with PR and the estrogen receptor (ER) often driving breast cancer growth and AR driving prostate cancer cell growth." (PMID 25188500, 2014). "What¿s more, p68 was found to be over-expressed in prostate cancers, to interact with AR, enhance AR transcriptional activity in luciferase reporter assays and to be recruited to the AR-responsive prostate specific antigen (PSA) promoter in the presence of RNAP II." (PMID 25150365, 2014). "In particular, Id4 could support the function of the AR as a suppressor of epithelial proliferation in the mature prostate, which is defective in prostate cancer." (PMID 23786676, 2013). "Indeed, the AR truncated variants are frequently found in CRPC tissues and induced by androgen deprivation in prostate cancer cells." (PMID 23896594, 2013). "To further characterize the mechanism by which CCAR1 contributes to transcriptional activation by NRs, we explored the possibility that CCAR1 may play a role in AR-mediated transcription and contribute to the tumorigenic potential of prostate cancer cells." (PMID 23887938, 2013). "Identification of the modifications that occur to these regions may increase our understanding of AR activation in prostate cancer and the role of AR in the progression from androgen-dependent to castration-resistant prostate cancer (CRPC)." (PMID 23863692, 2013). "Future studies focusing on identification of protein(s) that interface with AR in pre-RC may lead to the development of new and more effective strategies to suppress AR-dependent growth of prostate cancer." (PMID 23437213, 2013). "Similarly, 14-3-3eta has been shown to enhance androgen- and mitogen-induced androgen receptor transcriptional activity in castration-recurrent prostate cancer." (PMID 24103426, 2013). "An understanding of the mechanism of AR action in proliferation may lead to the development of effective strategies for the treatment of prostate cancer." (PMID 23437213, 2013). "Substantial numbers of patients receiving androgen-ablation therapy with androgen receptor antagonists may need subsequent surgery to treat complications of prostate cancer or for unrelated reasons." (PMID 24223137, 2013). "In accordance with this last hypothesis it has been published that PIM1-dependent phosphorylation of AR impacts in gene transcription and is prevalent in aggressive prostate cancer." (PMID 23565217, 2013). "Some researchers have proposed that susceptibility to prostate cancer is determined by heightened sensitivity toward androgens resulting from the number of CAG and GGC microsatellites in exon 1 of the androgen receptor gene and that the distribution of nucleotide polymorphisms is linked to ancestry." (PMID 23396824, 2013). "The androgen receptor (AR) is a member of the nuclear receptor (NR) superfamily of ligand-inducible DNA transcription factors, and is the major mediator of male sexual development, prostate growth and the pathogenesis of prostate cancer." (PMID 23566155, 2013). "Indeed, our studies clarify that androgen ligand-independent but AR-dependent c-Myc gene upregulation is a mechanism by which the AR protein promotes ligand-independent survival of prostate cancer cells." (PMID 23704919, 2013). "We recently demonstrated that a key transcription factor for lipogenesis, sterol regulatory element-binding protein-1 (SREBP-1), induced fatty acid and lipid accumulation and androgen receptor (AR) transcriptional activity, and also promoted prostate cancer cell growth and castration resistance." (PMID 23951060, 2013). "AR has a prosurvival function in androgen-dependent prostate cancer cells, which are susceptible to apoptosis without AR expression." (PMID 24201806, 2013).